CXCL10 (C-X-C motif chemokine ligand 10)
Diseases named in the same sentence as CXCL10 in open-access papers (continued):
Sharing a sentence is not in itself a finding about the gene and the disease.
colitis (continued). "Suppression of DSS-induced colitis by NOD2 activation was accompanied by reduced production of IFN-α and CXCL10 by colonic lamina propria mononuclear cells upon in vitro stimulation with lipopolysaccharide and CpG." (PMID 41155222, 2025). "While A2BR signaling mediates glial upregulation of Il6 and downregulation of Csf3, Cxcl1, and Cxcl10, glial A2BRs in colon tissue mediated the DSS colitis-induced increase in protein expression of all these mediators." (PMID 35869148, 2022). "During dextran sodium sulfate- (DSS-) induced colon inflammation and IFN-γ-treated macrophages, STAT1/IRF9 complex played a proinflammatory effect by regulating the transcription of CXCL10 gene." (PMID 34249133, 2021). "The expressions of ICAM-1, IL-1β, IL-16, CXCL10, MCP-1, CXCL9, CXCL12, and TIMP-1 were greatly reduced in MSC-EX-treated colitis group compared with those in the PBS-treated colitis group." (PMID 28842625, 2017). "CD69-deficient mice showed increased transcript levels of some chemokine genes, such as CCL-1, CXCL-10 and CCL-19 in steady-state conditions and after colitis induction." (PMID 23776480, 2013). "The discrepancy in regulation of CXCL10 also demonstrates the dissimilarity between human disease and TNBS-colitis." (PMID 23382912, 2013). "CXCL10 and its receptor CXCR3 have been shown to be upregulated in IL-10 knockout (IL-10−/−) mice and those with dextran sulphate sodium (DSS)-induced colitis." (PMID 20360984, 2010). "CXCR3 interactions with CXCL9, CXCL10 and CXCL11 are important for the selective homing of Th1 effectors cells, which mediate mucosal immunity, inflammation, and colitis." (PMID 18533024, 2008). "While neither NK nor NKT cell subsets largely expressed CXCR3, there were substantially more CXCL10+ NK cells in the MLN, PP, and LP during Mycobacteria-enhanced colitis, than compared to other groups." (PMID 18533024, 2008). "The current study suggests NK and NKT cells collaborate to produce CXCL10, IL-12p40, TNF-α, and IFN-γ to recruit and stimulate CXCR3+ leukocytes in either inductive or effector sites during colitis." (PMID 18533024, 2008). "Our results also suggest plasmacytoid > > myeloid DCs express CXCL9 and CXCL11, but less CXCL10 as well as IFN-γ to recruit, differentiate, and expand Th1 cells to mediate colitis." (PMID 18533024, 2008). "Blockade of CXCL10 ameliorated murine AIDS and acute colitis by inhibiting cell trafficking as well as inhibiting cell proliferation while supporting crypt epithelial cell survival." (PMID 18957084, 2008). "In addition, DEGs associated with the immune receptor (Lrrc19), cell chemotaxis (Ccr7, Cxcl1, Cxcl5, Cxcl9, and Cxcl10), and inflammatory response (IL1r11, IL11, Tnf, IL1β, and IL18) were also upregulated in the colonic tissue of colitis mice in DVF group." (PMID 38172943, 2024). "In addition, the upregulated expression levels of downstream genes in colitis mice after DVF challenge, including Cxcl9, Cxcl10, IL1β, and Tnf-α, were significantly decreased by typhaneoside." (PMID 38172943, 2024). "In contrast, it has been reported that IL-26 could protect mice against acute DSS-induced colitis, which is accompanied by reduced expression of TNF, CXCL9, and CXCL10, although its precise role in chronic colitis remains unclear." (PMID 35463017, 2022). "Moreover, the acute colitis produced a strong induction of mRNA expression levels of TNF-α, IL-1β, IL-6 and CXCL10, ranging from 233.5 ± 24.0% for IL6 to 663.5 ± 195.8% for TNF-α, in WTDSS mice compared to control group (p <0.05)." (PMID 34483912, 2021). "Cytokine protein arrays showed that the levels of several cytokines, including sICAM-1, IL-1β, IL-16, CXCL10, MCP-1, CXCL9, and TIMP-1, were upregulated (≥50-fold) in the colitis-induced PBS-treated group compared with those in the normal healthy control group." (PMID 28842625, 2017).
colitis (continued). "Furthermore, treatment of DSS-administrated CD69−/− mice with the mixture of CCL-1, CXCL-10 and CCL-19 neutralizing Abs significantly decreased the histopathological signs of colitis." (PMID 23776480, 2013). "Severity of the colitis could be ameliorated in DSS-administrated CD69-deficeint mice with the neutralization of CCL-1, CXCL-10 and CCL-19." (PMID 23776480, 2013). "The treatment of DSS-induced colitis in CD69−/− mice with the mixture of Abs that neutralize CCL-1, CXCL-10 and CCL-19 did not affect the accelerated body weight loss, but it reduced significantly the histopathological severity of the disease." (PMID 23776480, 2013). "PP and MLN DCs expressed elevated levels of CXCL9 and CXCL11, but not CXCL10, during Mycobacteria-enhanced colitis as indicated by their relative mean fluorescent intensities." (PMID 18533024, 2008). "We show that both Ccl5−/− and Cxcl10−/− mice are more resistant to DSS-induced colitis than WT mice by reducing immune cell infiltration, thus maintaining intestinal epithelial barrier function, consistent with previous reports that CCL5 is highly induced and plays a key role in DSS colitis model." (PMID 40749055, 2025). "Several in vivo studies indicated that anti-CXCL10 antibodies could inhibit epithelial ulceration in a UC murine model, attenuate inflammation in IL10−/− mice, and reduce colitis by compromising T helper type 1 (Th1) induction and recruitment." (PMID 36003333, 2022). "The results showed that the mRNA expression levels of Cgas, Il10, Cxcl10, Ifnb1, Tnf, Il6, and Il1b exhibited no obvious difference between GCV and vehicle treatment groups in DSS-colitis in STINGgt/gt mice (all p > 0.05)." (PMID 36467059, 2022).
ZIKV infection (56 papers, 2017 to 2025). "Using the same automated enzyme-linked immunosorbent assay workflow, IL-1β and CXCL10 were quantified after ZIKV infection through D11C (6 μg/mL)." (PMID 35862953, 2022). "A recent study has shown that acute ZIKV infection is associated with a peak of CXCL10 and CCL5 production, in infected patients." (PMID 31282298, 2019). "High-dimensional data analysis identified CXCL10 as the most promising biomarker for a putative clinical application - A heatmap matrix was constructed to evaluate the profile of biomarkers associated with ZIKV infection." (PMID 29768624, 2018). "Notably, CXCL10 has been implicated in both adult viral myocarditis and neuroinflammation during ZIKV infection, suggesting it may serve as a common mediator of ZIKV-induced tissue damage." (PMID 40762502, 2025). "A 25-plex ELISA, measuring 23 of the 34 cytokines we consider here, showed that ZIKV infection only significantly increased CXCL10 and CCL5 secretion and decreased CCL2 secretion from adult glioblastoma cells." (PMID 40240536, 2025). "We also observed a decrease in vascular endothelial growth factor (VEGF ) protein signal over time during ZIKV infection, which trends well with data showing that both type I interferons and CXCL10 block VEGF." (PMID 38440980, 2024). "In fact, accumulating evidence has suggested that significant increases in IFN-γ and CXCL10 levels during acute ZIKV infection are desirable for adequate induction of antiviral response, resulting in a mild illness." (PMID 37235332, 2023). "The CXCL10 is pointed as the most promising biomarker for acute ZIKV infection due to its overexpression." (PMID 36859461, 2023). "They demonstrated that there was the involvement of IL-17 and related cytokines, although they highlighted CXCL10 as a biomarker of acute ZIKV infection and a potential target for therapeutic intervention." (PMID 35215843, 2022). "Type II IFN (IFNγ) are key inducers of proinflammatory cytokines such as IRF1, IFIT1, CXCL10 and crucially, known cellular receptors for ZIKV infection such as AXL, Tyro3, and DC-SIGN." (PMID 35536870, 2022). "Taken together these findings suggest ZIKV-mediated increase of CXCL10 is conserved across several species, and lends support to the necessity for a local ZIKV infection that results in a ZIKV-specific increase of CXCL10." (PMID 34410903, 2021). "We thus evaluated CXCL10 expression levels post-ZIKV infection to establish if these models mimic CXCL10 induction observed in human disease." (PMID 34410903, 2021). "The systemic inflammatory response during the acute stage of Zika fever is characterized by high circulating levels of the cytokines and chemokines IL-9, IL-17A, and CXCL10." (PMID 33430059, 2021). "These authors revealed that the chemokines CXCL10, CCL2, and CCL8 were specifically associated with symptomatic ZIKV infection during pregnancy, and distinct immunoprofiles were detected in different trimesters in ZIKV-infected pregnant women." (PMID 33525328, 2021). "As anticipated, we found that ZY13 administration induced the expression of type I IFN-Ifnb, and its inducible genes such as Oasl, Cxcl10, and Ifitm3 at 6 hours post ZIKV infection." (PMID 32849457, 2020). "High-dimensional data analysis further identified CXCL10, a chemokine involved in foetal neuron apoptosis and Guillain-Barré syndrome, as the most promising biomarker of acute ZIKV infection for potential clinical application." (PMID 29768624, 2018). "In addition, ZIKV infection caused increased levels of cTnT, cTnI, CK, CK-MB, CCL2, CXCL9, and CXCL10—biomarkers associated with cardiovascular diseases and infarction-like myocardial pathology." (PMID 40762502, 2025). "Importantly, CCL2, CCL5, CXCL9, and CXCL10 were consistently elevated in both serum and heart tissue, indicating a systemic and localized inflammatory response induced by ZIKV infection." (PMID 40762502, 2025).
ZIKV infection (continued). "Additionally, genes encoding cytokines and chemokines, including IL-1α, Il-1β, Cxcr4, and Cxcl10, were significantly upregulated in response to ZIKV infection, suggesting the presence of neuroinflammation." (PMID 39273400, 2024). "Interestingly, CXCL9 and CXCL10 were the highest induced mRNA following ZIKV infection and was also induced but to a lesser degree by DENV." (PMID 37022660, 2023). "However, CXCL10 has been described as the most promising biomarker for acute ZIKV infection with it being involved in fetal neuronal apoptosis and Guillain-Barré syndrome." (PMID 35862953, 2022). "In our study, ZIKV infection was associated with the upregulation of IFNB, IFNL, and IFNG at the transcriptional levels, but significant protein production by ZIKV-infected DSCs was only observed for IFN-γ and IFN-γ-stimulated genes such CXCL10." (PMID 36483552, 2022). "Similar patterns of mRNA expression were also observed for TNF-α, IL-1β, IL-8 and CXCL-10 (IP-10) cell models following ZIKV infection; however, with a much higher level of IP-10 expression observed in the ZIKV-susceptible HASTR/ci35 cells compared with the ZIKV-resistant CCF-STTG1 cells." (PMID 35053142, 2022). "Interestingly, children with vertically transmitted ZIKV infection presenting microcephaly showed elevated CXCL-10 levels and CXCL-9 in cerebrospinal fluid obtained after birth; however, in our study, only CXCL-10 concentrations were decreased." (PMID 36146688, 2022). "Elevated CXCL10 levels have been suggested as a biomarker for ZIKV infection." (PMID 34410903, 2021). "Intriguingly, we detected the chemokines Cxcl10 and Ccl5 among genes upregulated by ZIKV infection." (PMID 33440758, 2021). "Furthermore, the overexpression of CXCL10 was recently identified as a potential serum biomarker of acute ZIKV infection." (PMID 31474994, 2019). "HBCA infection with another flavivirus, Zika virus, is associated with only limited activation of immune cytokine/chemokine response, but ZIKV infection induces the highest upregulation of CXCL10, IL-6, 8, 12, and CCL5 (RANTES), which corresponds with the observations in TBEV-infected HBCA." (PMID 31699097, 2019). "This study noted the induction of ATF3, EGR1, JUNB, IRF7, ISG15, HERC5/6, additional ISGs, chemokines CCL5 and CXCL10, prosurvival responses, and decreased proapoptotic genes, similar to gene induction levels we found to be induced by ZIKV infection of hBMECs (GEO GSE98889)." (PMID 28698279, 2017). "Adult patients in the acute phase of ZIKV infection produce high levels of chemokines such as CXCL3, CXCL9, CXCL10 and IL15 in the serum, as well as microcephaly babies in the cerebrospinal fluid, especially when developing neurological symptoms." (PMID 36142200, 2022). "Our results are consistent with the characteristic pattern of circulating CXCL10, CCL2, and CXCL9 chemokines during ZIKV infection." (PMID 33430059, 2021). "The only exception to this trend was found for CXCL10 in placenta cells, which was upregulated after STAT2 knockdown; however, this upregulation decreased somewhat after ZIKV infection." (PMID 30453684, 2018). "Increased serum concentrations of both CXCL (CXCL8 and CXCL10) and CCL chemokines (CCL2, CCL3, CCL4, CCL5, and CCL11) were found in acute ZIKV infection." (PMID 29768624, 2018). "Notably, ZIKV infection led to a 72-fold and 104-fold increase in CCL2 (marked with a red asterisk in 3A) and CXCL10 (notified by a black asterisk in 3A) levels, respectively." (PMID 40762502, 2025). "Both interferon-β and CXCL10 (IP-10), a chemoattractant molecule, were upregulated in the ZIKV infections, but not in HCMV infections." (PMID 38440980, 2024). "DEG assays and pathway analysis showed that ZIKV infection triggered strong activation of the TNF signaling pathway and upregulated the expression of several cytokines, including IP-10 (CXCL10)." (PMID 30228241, 2018).
ZIKV infection (continued). "Importantly, in all cases, the upregulation of these antiviral genes was stronger following USUV than ZIKV infection, up to 100 times for the chemokines CCL5, CXCL10 and for the IFN-Β." (PMID 28873445, 2017). "Additionally, we established that cross-reactive DENV antibodies enhance ZIKV infection in KU812 cells, which is selectively coupled to enhanced chemokine ligand 5 (CCL5), interleukin 1β (IL-1β), and C-X-C motif chemokine ligand 10 (CXCL10) secretion and inhibited granzyme B (GrB) secretion." (PMID 35862953, 2022). "The samples from pregnant women with ZIKV infection included in this study showed increases in all anti-inflammatory cytokines (IL-10), and some pro-inflammatory cytokines (IL-6, IFN-γ, IFN-α, and IL-17A), chemokines (CXCL10, CCL2, CXCL9, and CXCL8), and receptors (IL-1RA and IL-2R)." (PMID 33430059, 2021). "In the present study, we show that CXCL10 and CCL5 expression is strongly upregulated, particularly in infected undifferentiated hNPCs, suggesting that ZIKV infection induces a strong inflammatory response, which could lead to an immunocytoxic effect, particularly in undifferentiated cells." (PMID 31282298, 2019). "Therefore, we sought to determine whether ZIKV infection activates type I IFN transcription, which modulates the transcriptional activity of the IFN inducible genes such as MxA and CXCL10." (PMID 29167459, 2017). "Our findings suggest an important role of type-I interferon (IFN) response and chemokines CXCL10 and CXCL9 in the pathogenesis of microcephaly, which may represent a still unaddressed target with the potential to interrupt the destructive CNS inflammation induced by ZIKV infection." (PMID 31474994, 2019). "Absence of CXCL10, which is one of the ligands for CXCR3, did not affect protection levels implying that other CXCR3 ligands might be more critical for the recruitment of CD8 T cells in the context of ZIKV infection." (PMID 32973802, 2020).
colon carcinoma (54 papers, 2006 to 2025). "Nonetheless, CXCL10 can also recruit tumor-associated macrophages in colon cancer, which enhanced the progression of cancer and led to a poor outcome." (PMID 35755810, 2022). "Finally, clinical data demonstrates that expression of the CXCL10 is associated with increased metastatic potential in colon cancer, as well as in other types of cancer patients." (PMID 28878142, 2017). "In colon cancer, RFX1 expression was mainly negatively correlated with chemokine-associated immunokines, such as CXCL10 and CXCL11." (PMID 41425715, 2025). "Our current data demonstrate that FGFR4 induces CXCL10 production in colon cancer cells and that the secreted CXCL10 promotes CAF differentiation in a paracrine manner." (PMID 40447617, 2025). "We further explored CXCL9-Fc and CXCL10-Fc therapy in the CT26 colon cancer model in WT Balb/C mice." (PMID 39474427, 2024). "The recent data in colon cancer models are consistent with the prior finding that K17 expression in tumor cells enhances tumor cell intrinsic CXCL10 expression." (PMID 38140561, 2023). "In a syngeneic murine model of colon cancer, overexpression of CXCL10 suppresses tumor growth in vivo and decreases liver metastasis of colon cancer cells." (PMID 35207629, 2022). "For example, high expression of CXCL9 and CXCL10 is associated with increased numbers of tumor infiltrating CD8+ T cells, decreased metastasis, and improved survival in patients with ovarian and colon cancers." (PMID 31927532, 2020). "CXCL9 and CXCL10 were identified as T-cell homing factors in colon cancer, and increased CXCL11 expression is a marker for less aggressive disease." (PMID 29163806, 2017). "Forced expression of CXCR3 on colon cancer cells promoted lymph node metastasis, and CXCL10 enhanced invasive and migratory capacities of colon cancer cells in vitro." (PMID 29163806, 2017). "While chemokines are known to play a key role in the intestinal mucosal homeostasis and pathogenesis of inflammatory bowel diseases, chemokines such as CXCL9/MIG and CXCL10/IP-10 are overexpressed in colon cancer." (PMID 26951793, 2016). "The importance of CXCL10 produced by the cancer cells has been emphasized by a recent study comparing response to anti-PD-1 using colon cancer cells that are CXCL10high (CT26), and CXCL10low (Colon 26), showing that only the first respond to anti-PD-1 treatment." (PMID 39474427, 2024). "CXCL10 has been shown to synergize with TNF-α (also present in MPE) to induce EMT in colon cancer." (PMID 39114667, 2024). "Using immunologically »warm« murine syngeneic colon cancer models, CT26 and MC38, they demonstrated that overexpression of K17 in colon cancer cells was positively correlated with CXCL10 expression by cancer cells, T cell infiltration, and response to check point blockade therapy." (PMID 38140561, 2023). "Moreover, the association of cyclophosphamide with a TLR9 agonist increases the chemokine expression in murine colon tumors (Ccl5, Cxcl9 and Cxcl10) and CD8 T-cell proportion and inhibits tumor growth." (PMID 36429101, 2022). "Furthermore, in the Skrzypczak colorectal 2 dataset, the mRNA expression levels of CXCL10 were upregulated in colon carcinoma (fold change = 6.673, P = 3.40E-10)." (PMID 34233297, 2021). "Moreover, the higher the CXCL10 stimulation concentration was, the greater the upregulation of Snail protein expression in colon cancer cells." (PMID 34345201, 2021). "Earlier studies reported a prognostic role for CXCL9 and CXCL10 expression in colon cancer." (PMID 29163806, 2017). "However, the latest report has indicated that CXCL10 may promote the development of colon cancer by promoting cytokine-mediated mucosal damage and inflammation." (PMID 33144895, 2020). "In conclusion, FGFR4 in cancer cells promotes CXCL10 production via TLR3-IRF-IFNβ-dependent signaling that subsequently induces CAF differentiation and activation, culminating in colon cancer progression." (PMID 40447617, 2025).